CD34 (CD34 molecule)
Diseases named in the same sentence as CD34 in open-access papers (continued):
Sharing a sentence is not in itself a finding about the gene and the disease.
tumor (continued). "Immunohistochemically, the tumor cells were positive for CD-34 and negative for CDK4, MDM2, and P16." (PMID 40777097, 2024). "In both donors, B7-H3 expression was undetectable on resting CD34+ HSPCs but progressively increased from day 3 to day 14 of stimulation, across all progenitor populations, albeit at B7-H3 levels considerably lower than NCI-N87 tumor cells." (PMID 38717140, 2024). "This patient developed a partially solid and cystic lesion 17 months after gross total resection for PLNTY, with histological analysis of the recurrent tumour demonstrating a lack of CD34 expression and foci of high-grade features." (PMID 39294363, 2024). "ANGPTL4 overexpression could promote OC cell growth (tumor weight and volume) with higher expression of vimentin, proliferating cell nuclear antigen (PCNA), MMP9, ESM1 and CD34, which could be rescued by AG490." (PMID 38212795, 2024). "In the current case, the tumor cells were positive for CD31 but negative for CD34, along with the reported cases." (PMID 39687884, 2024). "All samples were positive for the soft‐tissue tumor marker Vimentin, as expected, and the CD34 endothelial cell marker was negative in tumor cells, only marking vessels." (PMID 37798904, 2024). "Immunohistochemically, the tumor cells showed diffuse positivity for S100, CD34, and vimentin; focal positivity for TFE-3; and negative expression of CD31, desmin, EMA, myogenin, cytokeratin (AE1/AE3), SMA, p63, SOX10, HMB45, pan-TRK, and cytokeratin 5/6." (PMID 39202049, 2024). "The absence of CD3, CD20, and CD34 in the tumor cells ruled out diagnoses of T-cell lymphoma, B-cell lymphoma, and angiosarcoma." (PMID 39473659, 2024). "Immunohistochemically, the tumor was positive for alpha-smooth muscle actin, but negative for CD34, desmin, keratin 18, S-100 protein, melan A, c-kit, and STAT6." (PMID 38805072, 2024). "Additionally, immunofluorescence analysis showed a lower MVD with decreased CD34 and CD31 expression in knocked down STAT3 tumor-bearing tissues." (PMID 38939041, 2024). "AQP1+CD34-αSMA- objects were single, S100+ and CD45- cells and are likely tumor cells." (PMID 38361951, 2024). "Moreover, it has been demonstrated in vitro that the endothelial CD34 + progenitor cells migrate to PC sites in response to high levels of pro-angiogenic factors such as VEGF and Angiopoietin-1, secreted by tumor cells." (PMID 39020414, 2024). "Conversely, ANGPTL4 inhibition significantly repressed the tumor weight and volume of SKOV3 cells with low vimentin, PCNA, MMP9, ESM1 and CD34 expression in comparison with the vector and NC groups, which could also be rescued by Colivelin." (PMID 38212795, 2024). "Among the markers of vascular origin, podoplanin was negative in all cases, while CD34 was positive in most cases (n = 7), with weak (n = 1) or moderate (n = 6) immunostaining in 5–30% of the tumor cells (average value of 10%)." (PMID 39451657, 2024). "Tumor cells express endothelial cell markers such as CD34, CD31, and ERG, and negative for mesothelial markers." (PMID 38115250, 2023). "There are no specific immunohistochemical reagents for this tumor; it can be positive for vimentin and CD34 and negative for S100." (PMID 37891997, 2023). "Detailed patterns of angiogenic and non-angiogenic tumor growth were evaluated by CD34 immunohistochemistry in whole tissue slides from 553 surgically treated patients with NSCLC stage I-IIIB disease." (PMID 37182191, 2023). "The increase in myeloid cells seen in huPDX3 was confirmed with another donor pool of CD34+ cells demonstrating that the increase in myeloid cells was not donor dependent, but instead driven by the tumor cells." (PMID 36860657, 2023).
tumor (continued). "Taking into account the results of our study and the authors’ reports, the presence of CD34+CD38− may be considered a predictive marker in BCP-ALL, which could be used to individualize the treatment in children with this type of neoplasm." (PMID 37675394, 2023). "To investigate this, we segregated the data population based on the expression of CD105, FAP and FSP mRNA and the absence of CD34 mRNA expression, considering that the data from these databases includes the entire tumor." (PMID 37719885, 2023). "tumor and/or ascitic fluid of 16 patients were characterized for MSCs phenotype (CD73, CD90, CD105), CSCs markers (CD24, CD44, CD133), and hematopoietic stem and progenitor marker (CD34) and leukocyte common antigen (CD45)." (PMID 37958844, 2023). "For example, CD34 is found in only 5–10% of SFTP, mainly in malignant and dedifferentiated tumours." (PMID 36769614, 2023). "Immunohistochemistry (IHC) showed tumor cells to be positive for CD34 and negative for AE1/AE3, S-100, desmin, SMA, h-caldesmon and CD-31." (PMID 37533000, 2023). "IHC revealed that the tumor cells were positive for desmin, S100, and myogenin, and negative for CD34, SMA, P63, and CK." (PMID 37233406, 2023). "Our data showed collected tumor samples remained viable for 5 days, and human tumor microenvironment/architecture including stroma/collagen (SMA and trichrome staining) and vascular endothelial cells (CD34 staining) were well-preserved for 5 days." (PMID 37713330, 2023). "The Lin−/c-Kit+/Sca-1+/CD34+ cells from the spleen of tumor-bearing animals expressed a unique inflammatory gene signature, including Tnf, Cxcl2, Nfkbiz, Nfkbia, compared to control BM (CBM) cells or tumor-bearing BM (TBM) cells." (PMID 37134077, 2023). "Immunohistochemically, the tumor cells were positive for CD34 and STAT6, and negative for smooth muscle actin, desmin, S100-protein, and epithelial membrane antigens." (PMID 37315497, 2023). "On IHC tumor cells were positive for CD34 and STAT6 while negative for AE1/E3, S-100 and beta-catenin." (PMID 37533000, 2023). "To determine whether our in vitro findings on cancer cell growth and survival can be translated in vivo, we employed humanized mice (NSG-hu CD34+), modeling a human immune system, to determine whether blocking the KYN pathway can suppress CR tumor growth." (PMID 37226257, 2023). "In our case, the tumor cells were diffusely immunoreactive for CD117, CD34, and DOG1." (PMID 37228978, 2023). "The tumor exhibited positive staining for STAT6 and CD34, suggesting SFT." (PMID 37315497, 2023). "The tumor showed extensive microcalcifications and cells with oval, nuclei and a clear perinuclear halo (A), positive immunostaining for OLIG-2 (B), GFAP (C), and CD34 (D), and intermingled Neu-N-positive neurons (E)." (PMID 37409721, 2023). "Similarly, multiple doses of CD34+ hematopoietic progenitor cell (HPC)-derived NK cells and IL-15 were given to animals bearing OvCa tumors treated with gemcitabine to improve tumor response." (PMID 37949944, 2023). "Based on the current literature, tumour to endothelial transdifferentiation can be identified by the expression of CD31 and/or CD34 in tumour cells, as absence of these markers is consistently reported in VM." (PMID 36823554, 2023). "Simultaneously, the different KIT exon 11 mutations such as point mutations, compound mutations and deletion mutations were not different based on gender, age, tumor location, CD117, CD34, DOG-1, bleeding or necrosis." (PMID 37901323, 2023). "On the other side, the CD34-positive fibroblasts dramatically decrease from normal breast stroma to tumor stroma, and they are wrongly considered to be absent inside stromal compartment surrounding malignant areas." (PMID 37568639, 2023).
tumor (continued). "As opposed to what was observed when CD34 immunostaining was employed, in tumors with high-intensity tumor budding, we did not observe differences in MVD, assessed by CD105 immunostaining, between the budding area and the area outside the budding." (PMID 36565216, 2023). "However, in samples with high-intensity tumor budding, the MVD assessed by immunostaining for CD34 was higher in the budding area than in the area outside the budding (p < 0.05)." (PMID 36565216, 2023). "Immunohistochemically revealed GFAP, vimentin, TTF1, CD34 and EMA-positive tumour cells." (PMID 36831464, 2023). "Immunohistochemically, the tumor cells were positive for smooth muscle actin but negative for c-kit, CD34, and S100." (PMID 37731837, 2023). "Others have reported an increase in human T-cell percentage over time in CD34+ HSC-engrafted humanized models, indicating that the effect is not human tumor dependent, but a characteristic of CD34+ HSC-engrafted humanized models." (PMID 36860657, 2023). "Tumor cells are highly immunoreactive for CD34, vimentin, bcl-2, and CD99, but these antigens are not specific." (PMID 37315497, 2023). "However, in tumors with high-intensity tumor budding, the MVD assessed by CD34 immunostaining was higher in the budding area than in the area outside the budding (p < 0.05)." (PMID 36565216, 2023). "AMBL was found to express ABCG2, ALDH1, BMI1, CD133, CD166, CD44, and c-Myc in peripheral and/or central cells of the parenchyma at variable extent and intensity levels, as well as CD34 in spindle-shaped stomal cells and LGR5 and NANOG in both epithelial and stromal tumor components." (PMID 37761874, 2023). "Untreated control liver showed moderate reactivity for CD34 in cirrhotic and tumor nodules while in the treated groups weak or negative reactivity was detected." (PMID 36874031, 2023). "In the N group, the expression of CD34 in tumor tissues was significantly lower than that in HCC tissues after nsPEF treatment, which indicated that nsPEFs had the effect of anti-angiogenesis in tumor therapy." (PMID 37234705, 2023). "Positive staining of melanin marker, CD34, CD1a, and SMA are helpful in diagnosing this tumor." (PMID 36800595, 2023). "We aim to study the interplay between TLSs and tumor stroma blood vessels (immature-CD34+/SMA−, versus mature-CD34+/SMA+), to find if this interrelation is BC subtype-specific and may influence lymphovascular and perineurial invasion and recurrence." (PMID 37190085, 2023). "It has been reported that in malignant cases where CD34 expression may be lost, demonstration of an SYT-SSX gene fusion may establish the renal origin of the tumor." (PMID 37927755, 2023). "Subsequently, pathological biopsy of the lymph nodes revealed high expression of CD163, CD68, S100, Lys and CD34 in the tumor cells and no expression of CD1a and CD207, confirming this rare clinical diagnosis." (PMID 36969238, 2023). "The majority of tumor cells were positive for CD117, DOG-1, and CD34, and the Ki-67 index was 8%." (PMID 37311038, 2023). "Immunohistochemically, the tumor cells were positive for CK, calretinin, D2-40, WT-1, and vimentin, and negative for Paird box 8, synaptophysin, chromogranin-A, inhibin-α, S-100, Melan-A, HMB45, and CD34." (PMID 38115250, 2023). "The correlation between the stage of tumor in the patients and their CD34 count was not significant (0.057, NS)." (PMID 38130549, 2023). "However, tumor-related genes (MKI67, CD34) and CAFs (FAP) were downregulated in the Nb-TriTE group compared with the other groups." (PMID 38031188, 2023). "Another option is a larger tumor area not visible on MRI and not included in the surgical field as indicated by the diffuse infiltration pattern of CD34- and p16-immunoreactive tumor satellites." (PMID 36973520, 2023).
tumor (continued). "Although the progenitor markers CD34 and TdT were absent, the neoplasm lacked CD20 and surface immunoglobulin (sIg) findings that can be seen with immaturity." (PMID 37555980, 2023). "A routine IHC antibody panel for BC evaluation does not usually include CD34 and αSMA due to the lack of their expression in tumor cells." (PMID 37568639, 2023). "Tumour cells in most other cases stained positive CD34, with the exception of PTs with myxoid feature which did not." (PMID 35906487, 2022). "The tumor cells showed immunopositivity for CD34, STAT-6, and no expression of CD99, AML, S-100, and Ki-67." (PMID 36426115, 2022). "Microscopic examination revealed that the tumor was spindle cell sarcoma, which was diffusely expressed of CD34, vimentin, S-100, and Pan-TRK, but negative for SOX10, EMA, SSTR2, PR, and STAT6." (PMID 35572973, 2022). "Tumor cells showed immunopositivity for CD34 and STAT-6 and no expression of CD99, AML, S-100, and Ki-67." (PMID 36426115, 2022). "Our study provides evidence that high tumor grade, subtotal tumor resection, CD34 negative immunostaining, and high Ki-67 index (>10%) were independent predictors for the poor prognosis of ISFTs." (PMID 35712477, 2022). "In CC mice with knockdown of linc00958, the tumor microvessel density biomarker CD34 and VEGFA were significantly inhibited, revealing that knockdown of linc00958 could attenuate tumor angiogenesis." (PMID 36056431, 2022). "The peptide shows stronger cytotoxicity against leukemic tumor cell lines (KG1-a and CCRF-CEM) than the normal cell lines (CD34+, HRECs and HACAT), which indicates that Smp24 may be a potential ACP." (PMID 35878176, 2022). "CD34 staining levels were lower in both the CTX-INS-GNP-treated group and the standard-of-care-treated group as compared to the untreated control, indicating that the treatments decreased tumor angiogenesis." (PMID 36324626, 2022). "Immunohistochemical staining indicated that the tumor was positive for STAT6, CD34." (PMID 36245559, 2022). "Immunostaining with anti-CD34 showed that in both CNE2 and SUNE1 tumor xenografts, tumors constructed with LBH-overexpressing cell lines presented markedly decreased MVDs in vascular hot spots compared to the negative controls, indicating attenuated angiogenesis in LBH-overexpressing tumors." (PMID 34975330, 2022). "Both SMA and CD34 highlighted the complex vascular network, but they were not expressed on the tumor cells." (PMID 35832542, 2022). "Meanwhile, CD105 can more specifically mark tumor angiogenesis without reacting with the original normal vascular ECs; thus, it is expected to be a new target for anti-tumor angiogenesis therapy in the future and a more ideal vascular EC marker compared with CD31 and CD34." (PMID 36185269, 2022). "The VM channels positive for PAS and negative for CD34 were lined with EBER-positive tumor cells and contained red blood cells." (PMID 35321317, 2022). "In addition, we found that the expression levels of VAV2, CD34, VEGF, and VE-cadherin in tumor tissues of the AKT18FGD5-AS1-Exos group were upregulated." (PMID 35528244, 2022). "Immunohistochemical staining of the tumour was positive for Renin, CD34, Vimentin, and synaptophysin (Syn) and negative for somatostatin receptor 2 (SSTR2) and chromogranin A (CgA)." (PMID 35303838, 2022). "After a fine-needle aspiration biopsy under endoscopic ultrasonography, the tumor was diagnosed as GIST with positive immunostaining for CD34 and c-kit and negative for alpha-SMA and S100." (PMID 35666331, 2022).
tumor (continued). "By applying CD34+ humanized NCG mice model and PCCA cell model analysis, we further found that Siah2 enhanced in vivo antitumor T-cell immunity in a PD-L1–dependent manner, unveiling a complex role of Siah2 in the tumor-immune microenvironment." (PMID 35154166, 2022). "Next, to confirm whether SOD3 expression is correlated with vascular maturation, we performed the multicolor visualization of IHC detection on CD34, SOD3, and VE-cadherin on the tumor tissue specimens of the two xenografts." (PMID 36359248, 2022). "Although DFSP has been shown to express the CD34 antigen and is one of the means of identifying the tumor, nodular areas of DFSP may have more sparse/variable expression of CD34." (PMID 35573491, 2022). "Finally, the xenograft tumour assay using nude mice showed that COMMD3 knockdown inhibited tumor growth and the expression of HIF1α, VEGF and CD34." (PMID 35399735, 2022). "Only a few dispersed CD34-ir normal and tumor cells were detected at long-term cultures (data not shown)." (PMID 35884847, 2022). "Of note, it was observed that the expression of common tumor angiogenesis markers of CD34 & CD105 was higher in high ARGs signature score group, moreover, ARGs signature score was positively with the expression of CD34 & CD105 (p < 0.001)." (PMID 35836112, 2022). "Immunochemical analysis revealed positive tumor staining for c-kit protein and alpha-smooth muscle actin and negative staining for CD34, desmin, and S-100 protein." (PMID 36214924, 2022). "The result found that progenitors of FGFR2+ fibrocytes (FGFR2+CD34+CD45+ cells) in BM were significantly increased in KYSE30 tumor-bearing mice when compared with non-tumor-bearing mice (P < 0.01)." (PMID 35941662, 2022). "Tumor cells were negative for, CD34, CD31, v-ets erythroblastosis virus E26 oncogene like isoform 2 (ERG), and FLI1." (PMID 35615157, 2022). "By IHC, the tumor cells were diffusely positive for TLE-1 and vimentin and focally positive for epithelial membrane antigen, AE1/3, Cam5.2, SATB2, and CD34 (all in less than 10% tumor cells)." (PMID 35125107, 2022). "This approach enables the study of a patient’s immune response with matched immune-tumor cell donors shortly after TIL or peripheral blood mononuclear cells (PBMC) injection, avoiding the long reconstitution time after CD34+ hematopoietic progenitor cell injection." (PMID 35804867, 2022). "Although CD34 expression was demonstrated to be an excellent biomarker to distinguish ACC from ACAc, in the present study, this is more likely related to steroid production capacity than with other tumor biological features." (PMID 35628389, 2022). "Our patient's tumor cells were negative for c‐kit and CD34, which are frequently expressed in GIST, which excluded metastasis of GIST with smooth muscle differentiation." (PMID 36545560, 2022). "Likewise, in animal studies, immunohistochemical detection of tumor tissue from in situ tumor-implanted mice showed a significant reduction in CD31-positive and CD34-positive endothelium (EC) in CLEC3B high-isogenic grafts." (PMID 35692794, 2022). "Tumour cells are positive with a range of endothelial markers including CD31, CD34, D2-40, and ERG." (PMID 34322734, 2022). "By contrast, in non-tumor livers, ACE2 is detected not only in the epithelial lining of bile ducts and within hepatocyte’s bile canaliculi, but also in the CLEC4M-positive sinusoidal endothelium and the CD34-positive capillary vessels of the periportal plexus." (PMID 35115564, 2022). "GIST was excluded because the tumor cells were negative for c‐kit and CD34, and mild atypia of the tumor with no mitotic activity or necrosis excluded leiomyosarcoma." (PMID 36545560, 2022).